RNU6-268P (RNA, U6 small nuclear 268, pseudogene)
Gene: Small nuclear RNA gene on chromosome 2 (230,752,141 to 230,752,247, forward strand). Ensembl gene ENSG00000201044.
Homologues: Orthologues: chimpanzee U6 (97% identical), macaque U6 (94% identical), mouse Gm25596 (84% identical), rat U6 (82% identical), pig U6 (79% identical). Paralogues in human: RNU6-480P (89% identical), RNU6-144P (88% identical), RNU6-11P (87% identical), RNU6-140P (87% identical), RNU6-16P (87% identical), RNU6-204P (87% identical), RNU6-21P (87% identical), RNU6-37P (87% identical), RNU6-80P (87% identical), RNU6-86P (87% identical), RNU6-1 (86% identical), RNU6-188P (86% identical), and 1286 more.